ERBB2 (erb-b2 receptor tyrosine kinase 2)
Diseases named in the same sentence as ERBB2 in open-access papers (continued):
Sharing a sentence is not in itself a finding about the gene and the disease.
breast cancer (continued). "Recently, by targeting Erb-B2 Receptor Tyrosine Kinase 2(HER2) gene, CRISPR-Cas9 has managed to inhibit cell proliferation and tumorigenicity in HER2-positive breast cancer cells, demonstrating its potency in clinical application." (PMID 31799189, 2019). "We noticed that ORMDL3 is only about 200 kb away from ERBB2/HER2, which is a well-known tumor driver in multiple cancers, including breast cancer." (PMID 30621577, 2019). "The tyrosine phosphorylation of EGFR was ablated in GRB7 knockdown ERBB2+ breast cancer, suggesting the effects of Grb7-mediated EGFR activation on the malignancy of ERBB2+ breast cancer." (PMID 31083325, 2019). "To investigate the synergistic effects of ErbB2 inhibitor and cholesterol-lowering drug in vivo, we generated ErbB2-positive breast cancer xenograft mouse models by implanting HCC1954 cells into athymic nude mice." (PMID 30786890, 2019). "To identify injury-induced changes in the plasma membrane proteome we used MCF7 breast cancer cells expressing a N-terminally truncated 95 kDa version of ErbB2 (p95ErbB2), which increases their membrane dynamics and invasiveness." (PMID 31040365, 2019). "In breast cancer, high expression of HuR exerts oncogenic function by increasing the stability of ERBB2 mRNA." (PMID 30691465, 2019). "Human epidermal growth factor receptor 2 (currently known as ERBB2, but referred to as HER2 in this study)–positive breast cancer is morphologically and genetically heterogeneous." (PMID 31002322, 2019). "Here, using multiple models of breast cancer driven by the oncogene ErbB2, we show that the tyrosine kinase c-Src links energy sufficiency with PRC2 overexpression via control of mRNA translation." (PMID 31263101, 2019). "High levels of mRNA encoding mammaglobin, CK-19 (keratin 19) and HER2/neu (Erb-B2 receptor tyrosine kinase 2), which are specific markers of breast cancer, are also found in the blood plasma of patients with given disease." (PMID 31572192, 2019). "Further, our identification of increased IL8, IL6, HAS2, and ICAM1, as well as decreased ERBB2 in MpBC samples matches findings from a microarray comparison of gene expression between metaplastic breast cancers and ductal carcinomas of the breast." (PMID 31488082, 2019). "The standard of care for early-stage ERBB2+ breast cancer is chemotherapy plus trastuzumab (HerceptinTM)." (PMID 30898150, 2019). "Collectively, these data confirm that Ezh2 overexpression and catalytic activity strongly promote the proliferation of ErbB2-driven breast cancer cells." (PMID 31263101, 2019). "Our study provides a first look at similarities and differences between the p140Cap protein’s interactomes in healthy specialized tissue (brain synaptosome) compared to an aggressive ERBB2 breast cancer model." (PMID 31681758, 2019). "Genentech’s trastuzumab (Herceptin) is one of the first antibody drugs for targeted therapy of breast cancer and targets the small ERBB2 extracellular domain." (PMID 31333463, 2019). "p130Cas overexpression in ErbB2 human breast cancer correlates with poor prognosis and metastasis formation." (PMID 30816273, 2019). "Taking advantage of this novel regulatory phenomenon, panitumumab, a humanized monoclonal antibody targeting EGFR, has been shown to significantly decrease the proliferation of ERBB2+ breast cancer." (PMID 31083325, 2019). "Trastuzumab (Herceptin) is a molecular targeted drug of ERBB2-positive metastatic/advanced breast cancer and gastric cancer." (PMID 30842786, 2019). "Taken together, our data demonstrate that ethanol can modulate ERBB2’s function in breast cancer via a novel interplay with STARD10." (PMID 30611309, 2019). "Based on the initial results of the BOLOERO-3 trial, it appears that such combination represents a promising therapeutic strategy to target patients with advanced ERBB2+ breast cancer developing resistance to conventional therapy." (PMID 30072418, 2019).
breast cancer (continued). "Human epidermal growth factor receptor 2 is known to play an important role in the progression of aggressive types of breast cancer, where the corresponding ERBB2 gene is shown to be amplified in 15–20% of cases." (PMID 30499260, 2019). "Both trastuzumab and pertuzumab are expected to have significant, cell-autonomous efficacy against ERBB2+ breast cancer cell lines, based upon their respective action against either ligand-independent or ligand-dependent ERBB2 signalling." (PMID 30898150, 2019). "In HBC, ERBB2 and TOP2α are frequently co-amplified and co-expressed in breast cancer patients and have also been proposed as prognostic biomarkers." (PMID 31301170, 2019). "The receptor tyrosine kinase HER2 (ErbB2) is overexpressed or amplified in 20–30% of breast cancer patients, correlating with cancer aggressiveness and reduced patient survival." (PMID 30833639, 2019). "Mechanistically, YY1 has been shown to coordinate with AP2 to induce the oncogene Erbb2 in breast cancer cells leading to tumor aggressiveness." (PMID 31824839, 2019). "Firstly, we analysed the use of ERBB2 amplification as a biomarker of response to different drugs (trastuzumab, pertuzumab and trastuzumab emtansine) in HER2 positive breast cancer." (PMID 31169290, 2019). "The effect of ERBB2 gene amplification and its concomitant overexpression (in terms of protein levels) on human breast cancer (HBC) patients is well documented." (PMID 31301170, 2019). "Two structurally unrelated Ezh2 inhibitors, GSK126 and EPZ643853, also significantly impaired the proliferation of ErbB2-driven breast cancer cells in vitro." (PMID 31263101, 2019). "For instance, our previous studies demonstrated that low-dose genistein exposure attenuated the cancer-preventing effects of tamoxifen in cell line and mouse models of ErbB2-overexpressing breast cancer." (PMID 31059536, 2019). "Activated NF-κB has been associated with tumor growth and drug resistance in ERBB2-positive breast cancer." (PMID 31796128, 2019). "When included in the first-line therapy with trastuzumab and chemotherapy, pertuzumab demonstrated a clinically meaningful improved survival for patients with metastatic ERBB2+ breast cancer and a smaller survival benefit in the adjuvant setting." (PMID 30898150, 2019). "In clinical trials, both GRB7 and ERBB2 have been indicated as two key genes in the 21 gene recurrence score assay to predict the recurrence of tamoxifen-treated breast cancer." (PMID 31083325, 2019). "In calling ERBB2 positivity in breast cancers using FISH, an ERBB2 ratio of 2.2 was used to call positivity, closely correlating with the assay threshold for amplification calling." (PMID 31040929, 2019). "HER2 + breast cancers overexpress ERBB2/HER2 which promotes proliferation by regulating CDKs and Cyclins." (PMID 32039208, 2019). "Next, we observed high protein expression of CHRNA9 and ERBB2, having an SSIM = 3.66 and displaying a strong association, in HER2-enriched breast cancer cell lines (e.g., BT474) compared with that in the other cell lines." (PMID 31311925, 2019). "Only with this type of design it will be possible to define the ERBB2 status (RNA and protein in both domains) in FMTs, contributing to validate the use of cat as a model for ERBB2-positive breast cancer studies." (PMID 31301170, 2019). "For example, we identify CHRNA9 with 12 PPIs (e.g., ERBB2) can be a therapeutic target and find its anti-metastasis agent, bupropion, for treatment in nicotine-induced breast cancer." (PMID 31311925, 2019). "The expression of murine ErbB2 in TS/A cells was exploited to provide experimental evidence of the oncosuppressor role of FoxP3 in mammary cancers, that downmodulated the expression of the ErbB2 oncogene." (PMID 31783695, 2019).
breast cancer (continued). "ErbB1-specific inhibitors have been proven to reduce ErbB2-signalling and growth of breast cancer cells that express high levels of ErbB2." (PMID 31905843, 2019). "In this setting, BETi re-sensitize breast cancer cells become resistant to ERBB2 inhibitor lapatinib, by suppressing the expression of alternative RTKs, including ERBB3, IGF1R, DDR1, MET, and FGFR." (PMID 30841549, 2019). "In epithelial cells, SEMA4D triggered invasive growth and stimulated migration in breast cancer cells in concert with ErbB-2 signaling." (PMID 31877778, 2019). "ErbB2 activation was observed in bladder, lung, gastric, ovarian, prostate, and breast cancer cells." (PMID 30917575, 2019). "In this work we evaluated the ERBB2 and TOP2α gene status and RNA levels in a collection of feline mammary tumors using the disease-free tissue sample collected from the same donor as reference and these data were associated with clinicopathological features." (PMID 31301170, 2019). "Among them, Trastuzumab was approved for the treatment of breast cancers overexpressing ErbB2, alone or in combination with standard chemotherapy." (PMID 30816273, 2019). "The overexpression of ERBB2, also commonly known as human epidermal growth factor receptor 2 (HER2), is widely associated with approximately 15–30% of breast cancers (HER2-positive)." (PMID 31835892, 2019). "Due to the identification of metastasis-acquired ERBB2 alterations in patients with breast cancer brain metastases, Grb7 has been recently indicated as one of the most recurrently upregulated genes in cancers." (PMID 31083325, 2019). "Overexpression/amplification of HER2 (ERBB2) is used to predict the response to monoclonal antibodies such as trastuzumab and pertuzumab in breast cancer and the response to trastuzumab in esophago-gastric adenocarcinoma." (PMID 31547595, 2019). "The migration and invasion enhancer 1 (MIEN1/C35/C17orf37) gene is close to the oncogene ERBB2 and has been considered an oncogene in breast cancer." (PMID 31581708, 2019). "Using biochemical and proteomic data, and bioinformatics tools, we were able to provide a first comprehensive analysis of the specific p140Cap PPI network in NeuT/ERBB2 breast cancer cells." (PMID 31681758, 2019). "We found that the ERBB2 mRNA expression was significantly lower in TPBCs than in ER-PR-HER2+ breast cancers." (PMID 31410192, 2019). "Collectively, these observations show how oncogene-dependent bioenergetic modulation, through reprogramming mRNA translation, drives epigenetic alterations that are essential for ErbB2-driven breast cancer." (PMID 31263101, 2019). "Biopsies were selected to represent all breast cancer subtypes, with a focus on the aggressive triple-negative tumors (N = 66 triple-negative; 22 Luminal A; 22 Luminal B; 34 ERBB2 [also known as HER2] positive)." (PMID 31434678, 2019). "More importantly, using ErbB2-positive breast cancer xenograft mouse models, we confirmed the potent synergistic effects of lovastatin and lapatinib to suppress the in vivo growth of HCC1954 xenografts." (PMID 30786890, 2019). "Each sample was labeled as one of five breast cancer subtypes: ‘basal-like’, ‘luminal A’, ‘luminal B’, ‘ERBB2’ and ‘normal breast-like’." (PMID 30010791, 2019). "Amplification of ErbB2 gene is frequently observed in cancer patients, which identifies a subgroup of breast cancers called Her2/ErbB2-positive that accounts for 20–30% of breast malignancies." (PMID 30786890, 2019). "A trivalent bispecific antibody targeting ErbB2 and CD16 was shown to be more potent than anti-ErbB2 single-chain variable fragment (scFv)-Fc fusion protein in vitro against breast cancer cell lines, and in vivo against breast cancer xenograft mouse model." (PMID 30805309, 2019).
breast cancer (continued). "When endogenous nectin-4 was immunoprecipitated using an anti-nectin-4 polyclonal Ab (pAb) in SUM190-PT breast cancer cells, endogenous ErbB2 was co-immunoprecipitated with endogenous nectin-4." (PMID 31831814, 2019). "The upregulation PD-L1 also correlated with better response to neoadjuvant chemotherapy in basal and ERBB2-enriched breast cancers." (PMID 31146499, 2019). "15–25% of breast tumors carry a high-level amplification of ERBB2, and ERBB2-overexpressing in breast cancer leads to substantially lower overall survival rates." (PMID 30621577, 2019). "We chose breast cancer cell lines with amplification of the ErbB2 locus which represent different breast cancer subtypes, in order to analyse the importance of nHER2 in both of these molecular environments." (PMID 31747426, 2019). "Copine 3 is found as a novel player in the regulation of ErbB2-dependent cancer cell motility in breast cancer T47D cells." (PMID 31487856, 2019). "This is the first report demonstrating that ethanol can modulate in dynamic manner the ERBB2 role through STARD10 involvement in breast cancer." (PMID 30611309, 2019). "It is known that breast cancer cells over-expressing ErbB2 depend on its activity for proliferation." (PMID 30858763, 2019). "Amplification or overexpression of the human epidermal growth factor receptor 2 (HER2/Erbb2) occurs in approximately 15–20% of human breast cancers." (PMID 30959874, 2019). "The predictive biomarkers in breast cancer are the estrogen (ER), progesterone (PR) receptors and human epidermal growth factor receptor HER2 (erbB2/neu) whose overexpression is associated with a lower probability of response to tamoxifen and trastuzumab." (PMID 30611309, 2019). "To this end, we investigated expression levels of the ERBB2 gene in two breast cancer cell lines—BT-474 and MCF-7—known to differ in the expression levels of HER2, the protein product of the ERBB2 gene." (PMID 31430289, 2019). "As expected, many established oncogenes in distinct malignancies were detected including ERBB2 in breast cancer, MET in stomach tumor and BCL2 in leukemia/lymphoma." (PMID 31050342, 2019). "Merkhofer and colleagues, in an attempt to elucidate the pathway leading to NF-κB activation, proved that ERBB2 requires IKKα to activate NF-κB through the canonical pathway independently of the PI3K pathway in ERBB2-positive breast cancer cells." (PMID 31796128, 2019). "FOXP3 promotes the immune evasion as Treg cell marker suppressing immune response against cancer, while FOXP3 at the Xp11.23 revealed good prognosis in breast cancers as a tumor suppressor by regulating HER-2/ErbB2 or SKP2 oncogene." (PMID 31815635, 2019). "In breast cancer, high level of expression of miR-125b has been shown to cause down-regulation of ERBB2 (HER2) and ERBB3 (HER3), and thereby suppression of tumor growth." (PMID 31360737, 2019). "So, too, overexpression of the ERBB2/Her2 oncogene in breast cancer-derived EV alters the vesicular contents toward a malignant phenotype." (PMID 30895170, 2019). "Trastuzumab is the first approved monoclonal antibody targeting ERBB2 for the treatment of ERBB2/HER2-positive breast cancers." (PMID 31817861, 2019). "HER2 (ErbB2), which is a transmembrane receptor with tyrosine kinase activity 7, is amplified and/or overexpressed in one fifth to a quarter of mammary cancers." (PMID 31534538, 2019). "A breast cancer patient with ERBB2 amplification switched from single agent trastuzumab to combination ado-trastuzumab + pertuzumab." (PMID 31384390, 2019). "In contrast with several above-mentioned MPs (e.g., CD44, EGFR/ERBB2, and APP) that have been well studied, the interacting partners and pathways associated with CHRNA9 in breast cancer remain to be elucidated." (PMID 31311925, 2019).
breast cancer (continued). "The cholesterol abundance was examined in ErbB2-positive breast cancer cells using filipin staining." (PMID 30786890, 2019). "For instance, mice lacking cyclin D1 or CDK4, as well as mice expressing mutant cyclin D1 (incapable of activating CDK4/6) were resistant to breast cancer induced by the Erbb2/HER2 oncogene." (PMID 30959874, 2019). "Based on these pivotal clinical trial results, this combination is now FDA approved for use in both early-stage neoadjuvant and adjuvant, and metastatic ERBB2+ breast cancer." (PMID 30898150, 2019). "Although the oncogenic properties of ErbB2 in breast cancer has been extensively investigated, the connection between its expression levels and the physical properties of breast cancer cell membranes is obscure." (PMID 30786890, 2019). "In breast cancers, FGFR4 is overexpressed in especially ERBB2/HER2-enriched tumors, where it has been linked to tumor growth and apoptosis resistance." (PMID 30903103, 2019). "We now demonstrate that inactivation of ERBB3/PI3K by these therapeutic antibodies is insufficient to inhibit the growth of ERBB2-amplified breast cancer cells." (PMID 30898150, 2019). "Here, we show that mTORC1 activation shapes the transcriptome at the epigenetic level by promoting the translation of PRC2 components, establishing an epigenetic landscape underpinning the progression of ErbB2-driven mammary tumors." (PMID 31263101, 2019). "Lapatinib, a TKI approved for breast cancers that overexpress HER2 (or ERBB2), has been shown to improve anti-tumor regorafenib properties against metastatic CRC." (PMID 31551425, 2019). "Trastuzumab, a humanized anti-ErbB2 antibody, is effective in the therapy of breast carcinoma, but it engenders cardiotoxicity and many cancer patients are resistant to Trastuzumab treatment." (PMID 31470510, 2019). "ERBB2-positive (ERBB2+) breast carcinomas comprise around 20% of BC cases, are defined by its amplification or overexpression, and indicate poor clinical prognosis." (PMID 31796128, 2019). "RANKL upregulated the phosphorylation and nuclear translocation of IKKα in a ERBB2-induced mammary carcinoma cell line." (PMID 31796128, 2019). "A validated target for breast cancer immunotherapy is ErbB2, a tyrosine kinase receptor (TKR) overexpressed on many carcinoma cells with a key role in the development of malignancies." (PMID 31470510, 2019). "RANK dimerization with ERBB2 seems to play a fundamental role in the progress of ERBB2-positive breast carcinomas." (PMID 31796128, 2019). "EMP3 mRNA is significantly upregulated in lymph node metastases of breast carcinomas, and is related to the levels of ErbB2 expression." (PMID 31652725, 2019). "The simplest molecular phenotypes are defined by single marker genes, like the estrogen receptor (ER), progesterone receptor (PR), or human epidermal growth factor receptor 2 (HER2/ERBB2) status of breast carcinomas." (PMID 31562358, 2019). "Intriguingly, STARD10 was found to be co-expressed with ERBB2 in several breast carcinoma cell lines, suggesting a selective growth advantage and cellular transformation for tumor expressing both proteins." (PMID 30611309, 2019). "Many breast cancers overexpress the receptor tyrosine kinase ErbB2 and several drugs that target ErbB2, such as trastuzumab and lapatinib, are used in the treatment of breast cancer." (PMID 30456204, 2018). "Here we conclude that MZF1 expression is needed for the ErbB2-induced, invasion-promoting anterograde lysosomal trafficking in breast cancer cells." (PMID 29396433, 2018). "The molecular profiling of patients with refractory metastatic tumors allowed identifying non previously detected ERBB2 amplifications in 6 out of 134 patients with breast cancers." (PMID 29515767, 2018).